KRAS (KRas proto-oncogene, GTPase)
Diseases named in the same sentence as KRAS in open-access papers (continued):
Sharing a sentence is not in itself a finding about the gene and the disease.
tumor (continued). "Furthermore, the enhanced proliferation aligns with the well-established role of mutant KRAS in promoting tumor growth and progression." (PMID 40244100, 2025). "Interestingly, oncogenic KRASG12D can be transferred to tumor cells via platelet-like particles leading to a growth advantage in KRAS wildtype cells." (PMID 40427186, 2025). "Genome-wide CRISPR-Cas9 knockout screens have shown that, when KRAS is activated, specific gene deletions can either accelerate or suppress tumor growth, revealing key metabolic weaknesses that could be targeted therapeutically." (PMID 40896696, 2025). "Finally, we assessed the relevance to human PDAC from KRAS mutant specimens containing tumor versus adjacent normal tissues." (PMID 40493403, 2025). "The shift away from M2 macrophages suggests that KRAS activation combined with chronic infection promotes a more inflammatory M1-like phenotype, which may have both tumor-promoting and tumor-suppressive effects depending on the stage of carcinogenesis." (PMID 40673273, 2025). "The tumor was KRAS, NRAS, and BRAF WT, and tumor mutational burden was 4 Mut/Mb." (PMID 41171165, 2025). "Moreover, copy-number alteration of KRAS, such as copy-number gain of oncogenic KRAS, loss of heterozygosity (LOH), or allelic imbalance can be beneficial for tumor growth." (PMID 39412982, 2025). "Since mutations in the KRAS gene are the earliest genetic variation in PDAC and lead to a loss of NK cells in precancerous stages, several strategies to enhance NK cell tumor infiltration and NK adoptive cell transfer are being explored as promising therapeutic interventions." (PMID 39859231, 2025). "It showed that epithelial KRAS-dependent stromal IL33 expression affected the pancreatic TME, as the loss of this cytokine increased CD8+ T cell infiltration and activation and, ultimately, reduced tumor growth, making IL33 another therapeutic target option." (PMID 40805153, 2025). "However, a significant association was observed between KRAS G12C mutations and HIF-1α expression in the tumor microenvironment, emphasizing the role of the tumor microenvironment in modulating disease progression." (PMID 39996842, 2025). "An increase in KRAS mRNA and protein levels could be related to higher proliferation of cells in the tumor tissue." (PMID 40596921, 2025). "The clinical deployment of KRAS G12C inhibitors has delineated a class-specific toxicity profile characterized by on-target, off-tumor gastrointestinal (GI) effects and clinically significant organ-specific adverse events that necessitate vigilant, agent-specific monitoring." (PMID 41170373, 2025). "The tumor was KRAS, NRAS, and BRAF WT, and the tumor mutational burden was 6 Mut/Mb." (PMID 41171165, 2025). "The absence of molecular and histopathological data, including microsatellite instability, KRAS/BRAF mutations, and tumor grade, limits the comprehensiveness of recurrence risk modeling and may contribute to residual confounding." (PMID 40936704, 2025). "One hypothesis is that KRAS protein measured in the patients with high levels mainly represent wildtype KRAS and therefore act as a tumor-suppressor, resulting in slower tumor growth and improved survival for the patients." (PMID 40596921, 2025).
tumor (continued). "KRAS promotes tumor growth, while NOXA triggers the apoptotic signaling pathway." (PMID 40913040, 2025). "While EGFR mutations typically arise in non-smokers and are correlated with non-inflamed tumor microenvironment, KRAS mutations are associated with tobacco smoking, high mutational burden, and immunologically more active tumors." (PMID 40524071, 2025). "HG106 inhibited SLC7A11 expression and tumor growth, especially in KRAS mutant LUAD61." (PMID 40765833, 2025). "However, mice in the MYC/KRAS chimeric siRNA–treated group continued to demonstrate significant tumor growth inhibition." (PMID 40762837, 2025). "Furthermore, ctDNA samples and tumor samples in the ctDNAhigh group showed a trend towards higher prevalence of 12p chromosomal gains (including KRAS) compared to the ctDNAlow group." (PMID 41044171, 2025). "These tumours also express tumour‐associated genetic markers (e.g., CD44v6, CDX2, BRAF) and immune markers (e.g., CD68, CD163), alongside characteristics like CpG island methylator phenotype and KRAS mutations." (PMID 40444502, 2025). "If confirmed, testing for miR-143 expression could become a routine part of the molecular workup for CRC, alongside KRAS and BRAF mutational analysis, to help oncologists tailor therapeutic strategies based on the tumor’s specific molecular vulnerabilities." (PMID 41450965, 2025). "Potential solutions to enhance KRAS-targeted TCR-T therapy include multi-antigen targeting to address tumor heterogeneity, universal TCR platforms for broader patient applicability, and advanced gene editing techniques like CRISPR/Cas9 to improve TCR specificity and reduce off-target effects." (PMID 40356763, 2025). "Recent studies indicate that measuring KRAS dosage can provide insights into tumor aggressiveness, guide treatment decisions, and improve personalized medicine, while emphasizing the need for standardized methods and integration with other biomarkers in clinical trials." (PMID 39906959, 2025). "Tumours collected after treatment exhibited a significant reduction in KRAS expression." (PMID 39820726, 2025). "In addition to their primary mechanisms, KRAS G12C inhibitors have been shown to remodel the tumor microenvironment through additional processes." (PMID 40303413, 2025). "Treatment of these pancreatic KRAS tumors has proven especially difficult due to dense desmoplastic stroma which denies effector immune cells or therapeutics access to the tumor, creating an immunosuppressive microenvironment and tumor that is invulnerable to immune checkpoint inhibition." (PMID 40943615, 2025). "However, the effect of oncogenic KRAS expression and subsequent inactivation in the tumor microenvironment in the lung remains unexplored." (PMID 39782689, 2025). "Additionally, Parabacteroides distasonis competes with F. nucleatum for DHX15 binding, and oral administration of P. distasonis in mice with KRAS p.G12D mutant CRC reduces tumor growth and F. nucleatum levels." (PMID 40231893, 2025).
tumor (continued). "In this case, no mutations were identified in the APC gene; however, a KRAS mutation (p.G13C) was detected, indicating a potential role in tumor pathogenesis due to its high VAF." (PMID 39939466, 2025). "Strategies under investigation include combination therapies with other immune modulators (e.g., LAG-3, TIGIT inhibitors), targeted therapies (e.g., EGFR or KRAS inhibitors), and epigenetic modulators that reprogram the tumor microenvironment to be more immunogenic." (PMID 41584608, 2025). "Variables that were not selected were age, sex, KRAS mutation status, primary tumor resection, and presence of peritoneal or liver lesions." (PMID 40305759, 2025). "Compared with non-KRAS G12D, KRAS G12D has been reported to be associated with lower PD-L1 expression, a lower tumor mutation burden (TMB), increased immunosuppression, and enhanced resistance to immune checkpoint inhibitors (ICIs)." (PMID 40296044, 2025). "First, they used the KRAS inhibitor RMC‐9945 to force tumor cells into the Lgr5+ state." (PMID 41346572, 2025). "Therefore, sustained oncogenic KRAS signaling is essential for maintaining progenitor-like epithelial states that also engage tumor suppressive responses in the injured pancreas." (PMID 40661354, 2025). "In addition, KRAS enhances tumor infiltration of MDSCs (myeloid-derived suppressor cells) and Tregs (regulatory T cells) through several mechanisms." (PMID 40885393, 2025). "This mini-review synthesizes recent advances defining how tumor-intrinsic mechanisms, such as KRAS-driven basal extrusion, epithelial–mesenchymal plasticity and chromosomal instability, cooperate with microenvironmental cues to promote early metastatic competence." (PMID 41394398, 2025). "An EGFR inhibitor is added if the tumor is wild-type for KRAS, NRAS, and BRAF." (PMID 40004690, 2025). "This suppression suggests that miR‐181a/d could be used as new therapeutic agents for HPV‐positive OSCC, particularly given their role in downregulating KRAS and exhibiting tumor‐suppressive properties." (PMID 41001946, 2025). "However, a higher LIMG score correlated with tumor location, MSI status, lower KRAS mutation frequency, and lower TMB." (PMID 40766310, 2025). "The KRAS oncogene is mutated in approximately 40% of CRC patients and typically associated with resistance to receptor tyrosine kinase inhibitors, distant metastasis, poor tumor differentiation and reduced survival rate." (PMID 40707783, 2025). "However, other relevant genes and signaling cascades are also involved in the tumor-suppressive function of wt KRAS and need to be further investigated." (PMID 40227826, 2025). "KRAS WT amplification was also observed in additional tumor types, albeit at lower frequencies." (PMID 39711431, 2025). "Many NS-LUAD tumours on the SD trajectory harbour KRAS mutations, but do not have an elevated mutation burden overall." (PMID 41509216, 2025). "Tumor suppressor miRNAs can interact with oncogenic KRAS, thereby inhibiting RAS/MAPK signaling." (PMID 39795030, 2025).
tumor (continued). "Additionally, abnormal activation of β- catenin (CTNNB1ex3) has been shown to synergize with KRAS to enhance tumor formation." (PMID 40275403, 2025). "So, a dual therapeutic approach combining KRAS inhibitors with NOS2 inhibitors could enhance the anti-tumour response." (PMID 40567499, 2025). "Despite the well-described structure, signaling, and regulation of KRAS in cancer, KRAS mutations are neither equally prevalent in different tumor types nor exert similar biochemical effects." (PMID 41309533, 2025). "In the EP group, 12 tumours had pathogenic mutations in key genes associated with response to anti‐EGFR therapy (1 × in BRAF + PTEN, 1 × in BRAF + PIK3CA, 2 × in BRAF, 3 × in PTEN, 2 × in NRAS, 1 × in KRAS, 1 × in HRAS and 1 × in PIK3CA)." (PMID 40302146, 2025). "The study also showed that IL-1β blockade could prevent particulate matter-induced tumor formation in mouse models with EGFR and KRAS mutations." (PMID 40940992, 2025). "Moreover, MRTX1133 has demonstrated significant tumor regression in immunocompetent models of KRAS G12D, leading to either complete or nearly complete remission." (PMID 40805153, 2025). "In addition to reducing proliferation, BAY-293 was able to induce programmed cell death in ATC tumor cells by disrupting survival signals mediated through KRAS." (PMID 40141222, 2025). "A similar pattern was observed in KRAS‐stratified analysis: PHGDH was positively correlated with proliferative pathways in both KRAS‐mutant and wild‐type groups, while it showed a negative correlation with inflammation‐related pathways specifically in KRAS wild‐type tumours." (PMID 40660426, 2025). "Alternatively, reducing tumor cell burden via surgery may enhance the effectiveness of adjuvant KRAS inhibitors." (PMID 40662364, 2025). "Preclinical data have suggested that the combinatorial targeting of EGFR and KRAS G12C leverages a dual-pathway blockade to inhibit tumor growth more effectively and may overcome the adaptive resistance to KRAS G12C inhibition." (PMID 40361439, 2025). "This enhanced ADCC, which was observed regardless of the tumor’s KRAS mutation status, is linked to a restoration of the apoptotic cascade, evidenced by a rise in caspase-3/7 activity and a reduction in the anti-apoptotic protein Bcl-2." (PMID 41450965, 2025). "Direct binding and repression of KRAS by miR-1 have been demonstrated in several tumor types, suggesting that KRAS may also contribute to miR-1-mediated tumor suppression in CCA." (PMID 41373864, 2025). "In addition, subcutaneous xenograft tumor models using DLD1 cells harboring mutant (G13D/−), wild-type (+/–) or both KRAS alleles (G13D/+) further indicated that GRAMD1A knock-down showed more pronounced effect on tumor volume and weight in KRAS mutant tumors." (PMID 40707783, 2025). "This is in line with our findings, where both KRAS and oxidative metabolism influence the autophagy-stemness axis in A549 and H1299 spheroid cells, modulating autophagic flux and regulating the stem cell-like characteristics of tumor cells." (PMID 40886002, 2025). "Yet, further studies are needed to explore how both the absence of the wt allele and increased dosage of oncogenic KRAS affect the interaction of tumor cells with the stromal and inflammatory microenvironment." (PMID 40227826, 2025).
tumor (continued). "In conclusion, discovery of the tumor-specific and mutant KRAS-reactive TCRs in the presented cases implies that our strategy to identify and select tumor-specific TCRs can be applied to many patients with different tumors, provided that surgical material for analysis is available." (PMID 40165973, 2025). "In mouse xenograft models with various KRAS mutations (G12C, G12D, G12V, A146V), BI-2865 inhibited tumor growth without visible adverse effects on animal body weight." (PMID 40805153, 2025). "Moreover, KRAS remodels the immune microenvironment by influencing tumor metabolism, an important route for immunomodulation." (PMID 41184283, 2025). "However, there was also upregulation of mTORC1, KRAS, complement, and cholesterol homeostasis signatures, which are known to be crucial for tumor maintenance and progression." (PMID 41256671, 2025). "Pathogenic somatic KRAS and PIK3CA mutations were identified via WES of the original MLA tumor." (PMID 41311737, 2025). "Mechanisms of tumor resistance to KRAS inhibition remain poorly understood." (PMID 40859018, 2025). "Moreover, we observed that the combination of 5-Fu with cetuximab and Remodelin increased tumor regression in our xenograft mouse model of wild-type KRAS/NRAS/BRAF CRC." (PMID 39905540, 2025). "Notably, cured mice exhibited strong adaptive immune memory upon rechallenge with homozygous KRAS G12D tumor cells." (PMID 40303413, 2025). "KRAS mutations drive tumorigenesis by activating cell signaling pathways, such as RAF-MEK-ERK and PI3K-AKT-mTOR, while also promoting angiogenesis and immune evasion in the tumor microenvironment (TME)." (PMID 40576713, 2025). "In addition, KRAS knockdown inhibited FHL3-mediated promotion of subcutaneous tumor growth in mice, with a low percentage of Ki67-positive tumors." (PMID 41184244, 2025). "While foundational methods like Sanger sequencing laid the groundwork for KRAS analysis, their clinical utility has dwindled in the precision medicine era due to inherent limitations in their sensitivity, particularly in mixed tumor samples or degraded specimens." (PMID 41514544, 2025). "KRAS WT amplification correlated with KRAS mRNA expression across this panel of cell lines (Spearman R = 0.98; P value = 8.4e−06), in line with published data obtained from patient-derived tumor samples." (PMID 39711431, 2025). "The C2 subgroup of tumor cells we identified is upregulated in KRAS signaling pathway." (PMID 39895784, 2025). "Additionally, inclusion of 4 copies of each KRAS neoantigen into the KRAS-focused cassette further elevated the KRAS neoantigen-specific T cell response, suggesting antigen density can amplify the magnitude of anti-tumor T cell responses." (PMID 41542091, 2025). "Additionally, 18% of KRAS-mutant tumours exhibited increased phosphorylation of ER alpha, supporting potential treatment strategies targeting multiple pathways." (PMID 40849356, 2025). "The univariate analysis shows that patient age, CEA level, lymphocyte count, albumin, NLR, SII, PNI, tumor distance from the anus, tumor size, tumor invasion of the intestinal wall, cT stage, cN stage, TRG grade, KRAS status, and microsatellite status are associated with survival." (PMID 40444087, 2025).